SLC22A3 (solute carrier family 22 member 3)
Diseases named in the same sentence as SLC22A3 in open-access papers (continued):
Sharing a sentence is not in itself a finding about the gene and the disease.
tumor (continued). "Whether SLC22A3 is also involved in the development of acquired platinum resistance will be the main issue for our next study to explore and we can start from comparing the differential SLC22A3 expression between recurrent tumor and primary tumor." (PMID 29088791, 2017). "Moreover, specific antibodies were used to detect SLC22A1, SLC22A2 and SLC22A3 protein by immunofluoresence confocal laser scanning microscopy in HCC tumor tissue (n = 7 from HCC cohort 1) and histologically normal liver tissue (n = 5 from IKP-liverbank) derived from patients without HCC." (PMID 22196450, 2011). "OCT1 (SLC22A1) and OCT3 (SLC22A3) mRNA expression was measured in primary human HCC and corresponding non neoplastic tumor surrounding tissue (TST) by real time PCR (n = 53)." (PMID 22439694, 2012). "Regarding the protein levels of these genes, SLC2A1, MMP14, TOP2A, ANLN, and SLC22A3 exhibited higher expression in tumor samples compared to normal samples." (PMID 37604837, 2023). "However, only a few coding RNA editing sites have been characterized, such as AZIN1, GABRA3, FLNB, SLC22A3, and COPA, which can affect tumor progression." (PMID 36895481, 2023). "A subgroup analysis of patients treated with regimens based on nucleoside analogs suggested that patients with negative brush border staining or apical localization of SLC22A3 in tumor cells have worse overall survival." (PMID 31874997, 2019). "DNA methylation, quantified by MALDI-TOF mass spectrometry and gene expression of SLC22A1, SLC22A2 and SLC22A3 were investigated using fresh-frozen HCC (n = 22) and non-tumor adjacent liver tissues as well as histologically normal liver samples (n = 120) from a large-scale liverbank." (PMID 22196450, 2011). "The results suggested that, the high expression of C1orf74, HK2, SLC22A3, SNX10 and URB2 and Neutrophils, as well as the low expression of RASSF5 and CD8+ T cells was related to the poor prognosis of CC patients, which might serve as the key prognostic biomarkers of tumor." (PMID 36354693, 2022). "However, there was no significance in tumor characteristics for the SLC22A3 expression." (PMID 22439694, 2012). "In contrast, SLC22A3 methylation was generally not different between HCC tissues and adjacent non-tumor liver tissue." (PMID 22196450, 2011). "PDAC patients with negative IHC brush border staining of SLC22A3 had significantly shorter PFS (P = 0.041, Log Rank and P = 0.024, Breslow) and OS (P = 0.007, Log Rank and P = 0.020, Breslow) than patients with positive staining in tumor cells." (PMID 31874997, 2019). "Therefore, these tumor cell lines seemed not to be suited for the investigation of SLC22A1 and SLC22A3 expression in vitro." (PMID 22439694, 2012).
cardiovascular disease (6 papers, 2017 to 2024). "Previous studies showed that PHACTR1 and SLC22A3 are involved in coronary vascular development and are key determinants of cardiovascular disease risk." (PMID 27893421, 2017). "SLC22A3 has been previously implicated in hypercholesteremia and cardiovascular disorders." (PMID 39120300, 2024).
SLC22A3 also shares sentences with these, for which no sentence is quoted: colon carcinoma (3 papers); Hypertension (3); cervical adenocarcinoma (2); esophageal cancer (2); liver cancer (2); prostate tumor (2); acute myeloid leukemia (1); benign prostatic hyperplasia (1); bladder cancer (1); cerebrovascular diseases (1); colon adenocarcinoma (1); diabetic retinopathy (1); digestive tumors (1); duodenitis (1); esophageal disorder (1); gastric cancer (1); gastritis (1); gastroesophageal reflux (1); glioblastoma (1); Ischaemic Stroke (1); joint diseases (1); kidney carcinoma (1); lung carcinoma (1); oesophageal cancer (1); pancreatic adenocarcinoma (1); prostate adenocarcinoma (1).